HGF (hepatocyte growth factor)
Description:
Potent mitogen for mature parenchymal hepatocyte cells, seems to be a hepatotrophic factor, and acts as a growth factor for a broad spectrum of tissues and cell types. Activating ligand for the receptor tyrosine kinase MET by binding to it and promoting its dimerization. Activates MAPK signaling following TMPRSS13 cleavage and activation.
Synonyms: SF; HPTA; F-TCF; HGFB; DFNB39
Tractability: Small molecule: a structure with a bound ligand is known; it has a high-quality binding pocket; it belongs to a druggable protein family. Antibody: a drug acting on it is in phase 2 or 3 trials; its Gene Ontology location is reachable by antibodies, with high confidence; UniProt predicts a signal peptide or a membrane-spanning region. PROTAC: a small molecule that binds it is known.
Target class: Secreted protein
Gene: Protein-coding gene on chromosome 7 (81,699,010 to 81,770,438, reverse strand). Ensembl gene ENSG00000019991.
Pathways (Reactome):
Signal Transduction: Drug-mediated inhibition of MET activation; MET Receptor Activation; MET activates PI3K/AKT signaling; MET activates PTK2 signaling; MET activates PTPN11; MET activates RAP1 and RAC1; MET activates RAS signaling; MET activates STAT3; MET interacts with TNS proteins; MET receptor recycling; Negative regulation of MET activity; PI5P, PP2A and IER3 Regulate PI3K/AKT Signaling; PIP3 activates AKT signaling; RAF/MAP kinase cascade
Immune System: Interleukin-4 and Interleukin-13 signaling; Interleukin-7 signaling
Disease: Constitutive Signaling by Aberrant PI3K in Cancer
Hemostasis: Platelet degranulation
Gene Ontology:
Molecular function: chemoattractant activity; identical protein binding; protein binding; endopeptidase activity; growth factor activity; serine-type endopeptidase activity; signaling receptor binding
Biological process: cell chemotaxis; cellular response to hepatocyte growth factor stimulus; hepatocyte growth factor receptor signaling pathway; negative regulation of hydrogen peroxide-mediated programmed cell death; negative regulation of release of cytochrome c from mitochondria; positive regulation of cell migration; positive regulation of DNA biosynthetic process; positive regulation of MAPK cascade; positive regulation of phosphatidylinositol 3-kinase/protein kinase B signal transduction; regulation of branching involved in salivary gland morphogenesis by mesenchymal-epithelial signaling; epithelial to mesenchymal transition; mitotic cell cycle; negative regulation of apoptotic process; negative regulation of autophagy; positive regulation of osteoblast differentiation; positive regulation of transcription by RNA polymerase II; proteolysis; animal organ development; positive chemotaxis; regulation of anatomical structure morphogenesis; regulation of multicellular organismal process; signal transduction
Cellular component: membrane; extracellular region; platelet alpha granule lumen
Genetic constraint (gnomAD): Loss-of-function variants: 24 observed, 71.59 expected, observed/expected ratio (o/e) 0.34, 90% interval 0.24 to 0.47. The upper end of that interval is the gene's LOEUF score, 0.47, which puts it in group 2 of 6, group 1 being the genes least tolerant of losing a copy. Missense variants: 499 observed, 634.37 expected, observed/expected ratio (o/e) 0.79, 90% interval 0.73 to 0.85. Synonymous variants: 194 observed, 210.62 expected, observed/expected ratio (o/e) 0.92, 90% interval 0.82 to 1.04.
Gene-disease validity (ClinGen):
ClinGen rates the evidence that HGF causes each of these diseases.
nonsyndromic genetic hearing loss (autosomal recessive): Moderate.
Homologues: Orthologues: chimpanzee HGF (99% identical), macaque HGF (98% identical), pig HGF (94% identical), rabbit HGF (93% identical), dog HGF (93% identical), guinea pig HGF (91% identical), mouse Hgf (91% identical), rat Hgf (90% identical), tropical clawed frog hgf (67% identical), zebrafish hgfb (45% identical), zebrafish hgfa (45% identical), Drosophila melanogaster CG14780 (9% identical), and 10 more. Paralogues in human: MST1 (43% identical), HABP2 (18% identical), GZMA (9% identical), GZMK (8% identical), PIK3IP1 (7% identical).
Diseases named in the same sentence as HGF in open-access papers:
HGF is named in the same sentence as 663 diseases in open-access papers, as found by Europe PMC text mining. Sharing a sentence is not in itself a finding about the gene and the disease. The quoted sentences say what the papers report.
breast carcinoma (318 papers, 1999 to 2026). "In our study, LAP, TGF-β1, and HGF exhibited significant interactions, suggesting potential synergistic mechanisms in modulating breast cancer risk." (PMID 40665092, 2025). "A potential causal effect of HGF on breast cancer was observed using IVs with suggestive GWAS significance (OR = 1.05, 95% CI = 1.00–1.09) and the effect was particularly stronger for ER negative breast cancer (OR = 1.08, 95% CI = 1.01–1.16)." (PMID 40665092, 2025). "Here, we found that CCL2/HGF-mediated glycolysis was shown to be associated with alterations in nucleotide metabolism in breast cancer cells." (PMID 40736024, 2025). "The use of two nested case–control studies in prospective cohorts enhances the robustness of our findings and supports causal inferences regarding the relationship between HGF and breast cancer." (PMID 40665092, 2025). "For instance, circulating IGF2 levels associate with increased risk of ER-positive breast cancer, while tissue HGF overexpression correlates with lymph node metastasis and serves as a prognostic indicator in breast cancer." (PMID 40804939, 2025). "Further stratification by time before breast cancer diagnosis demonstrated that among postmenopausal women diagnosed within five years, HGF remained significantly associated with breast cancer (1.19, 1.03–1.37)." (PMID 40665092, 2025). "A higher level of circulating HGF was reported previously among breast cancer patients, confirming HGF as a short-term risk biomarker for breast cancer." (PMID 40665092, 2025). "This growth factor is commonly produced by stromal cells such as fibroblasts and also by colorectal and breast cancer cells due to HGF promoter region mutations." (PMID 35626056, 2022). "By affecting the HGF/c-met pathway, OC caused the decrease of cell viability and malignancy in human breast cancer cells and in human prostate cancer cells." (PMID 36139836, 2022). "In a similar way, serum HGF, measured by ELISA, was correlated with a poor prognosis and a high risk of progression in metastatic (n = 34) breast cancer patients." (PMID 35818030, 2022). "Using this signature, HGF positivity is associated with aggressive breast cancer subtypes and is strongly associated with basal-like subtype." (PMID 34344422, 2021). "Invasive human breast cancer has been associated with high amounts of HGF (mesenchymal-derived cytokine) and Met, making them prospective therapeutic targets for the illness." (PMID 34768930, 2021). "Promoter in gastric cancer in association with α3 integrins.Promoter in breast cancer in association with integrins promoting a signaling pathway (HGF/c-MET).Promoter in liver cancer by increasing Rac/Cdc42 activity." (PMID 34830819, 2021). "In other studies of breast cancer, high expression of HGF has been associated with either poor or favourable prognosis and high levels of HGF in serum were associated with longer relapse‐free survival after neoadjuvant chemotherapy." (PMID 32946618, 2020). "In ER status‐stratified analyses, there was evidence for an association of HGF with ER− breast cancer risk [odds ratio (OR) per standard deviation (SD) increase: 1.17, 95% confidence interval (CI): 1.01–1.35; p = 0.035]." (PMID 32134113, 2020). "We investigated the importance of HGF, pMET and pAkt for the risk of ipsilateral breast tumour recurrence after adjuvant radiotherapy in primary breast cancer in tumours from the SweBCG91‐RT randomised trial." (PMID 32946618, 2020). "Reports have demonstrated that HGF/c-Met signalling plays an important part in breast cancer progression and that their expression is linked to poor patient outcome." (PMID 30314527, 2018). "Hepatocyte growth factor and its partner c-Met play a definitive role in the development and progression of breast cancers, as well as being implicated in particularly invasive and metastatic cancers." (PMID 30314527, 2018).
breast carcinoma (continued). "The events associated with HGF-induced breast cancer cell metastasis are triggered through HGF coupling with c-Met and the subsequent activation of signalling pathways that promote tumour progression." (PMID 30314527, 2018). "This study suggests the loss of EcSOD in breast cancer plays a pivotal role in promoting the HGF/c-Met-mediated cancer-fibroblast interactions." (PMID 29296173, 2017). "In the case of breast cancer, experimental studies have linked the reduced pericyte coverage with a hypoxic tumor state promoting an invasive HGF/c-met-dependent phenotype." (PMID 27248825, 2016). "Numerous studies have sought to uncover the mechanisms through which HGF/c-Met signalling contributes to the migratory and invasive phenotype in breast cancer, particularly focusing on pathways associated with epithelial adhesion." (PMID 25887320, 2015). "A variety of breast cancer cell lines (BCLs) have been used to study the role of HGF and c-Met in a range of cellular processes implicated in the progression of breast cancer." (PMID 25887320, 2015). "HGF/Met signaling has recently been associated with basal-type breast cancers, which are thought to originate from progenitor cells residing in the luminal compartment of the mammary epithelium." (PMID 26165517, 2015). "We will show that the HGF/c-Met pathway is associated with breast cancer progression and suggest that there is a firm basis for continued development of anti-c-Met treatment, particularly for patients with basal-like and triple-negative breast cancer." (PMID 25887320, 2015). "A truncation mutation in the deoxyadenosine tract element activates the HGF promoter in breast cancer cells, leading to the formation of an HGF/c-Met autocrine loop." (PMID 25887320, 2015). "The DATE element is thought to be a hot spot for promoter mutations leading to HGF dysregulation in breast cancer." (PMID 28548073, 2014). "Accordingly, high level of HGF in the plasma has been reported as an independent prognostic indicator of overall-survival and is associated with venous dissemination in breast cancer." (PMID 25230070, 2014). "We found that the women homozygous for the minor allele of HGF SNP rs5745752 had a higher risk of breast cancer whereas the major allele was significantly protective." (PMID 25029565, 2014). "TMPRSS3 SNPs rs3814903 and rs11203200, TMPRSS7 SNP rs1844925, and HGF SNP rs5745752 associated significantly with breast cancer risk (Poverall = 0.029, 0.008, 0.042, and 0.017, respectively)." (PMID 25029565, 2014). "Western blot analysis results showed that (-)-oleocanthal treatment caused a dose-dependent inhibition of HGF-induced phosphorylation of c-Met in the three breast cancer cell lines investigated." (PMID 24849787, 2014). "MTT assay results after 72 h treatment showed that HGF caused a dose-dependent increase in breast cancer cells proliferation and the maximum effect was identified at 40 ng/ml of HGF (comparable to 100 ng/ml) in all three breast cancer cell lines." (PMID 24849787, 2014). "To find out what was the compound in LX2 supernatants that caused sorafenib resistance, we screened the concentration of HGF in LX2 supernatants which was reported to cause elotinib resistance in breast cancer." (PMID 25057499, 2014). "Occurrence of high levels of HGF in breast cancer biopsies is associated with an aggressive malignant phenotype." (PMID 26932375, 2014). "In this study, we genotyped 82 tagSNPs from seven serine protease genes and HGF and evaluated their role in breast cancer risk and survival." (PMID 25029565, 2014). "SNPs in TMPRSS3 (rs3814903 and rs11203200), TMPRSS7 (rs1844925), and HGF (rs5745752) associated significantly with breast cancer risk (Ptrend = 0.008–0.042)." (PMID 25029565, 2014). "Previous studies show that elevated circulating HGF levels correlate with lower survival rates and increased risk of metastasis in breast cancer patients." (PMID 26932375, 2014).
breast carcinoma (continued). "The inhibition of mammary cancer cell growth was associated with the ability of (-)-oleocanthal treatment to block c-Met receptor activation in response to its natural ligand HGF in MDA-MB-231, MCF-7, and BT474 cancer cell lines in culture." (PMID 24849787, 2014). "In breast cancer, Met is thought to be activated through association with co-receptors or by binding to its ligand HGF produced by the tumor-associated stromal cells." (PMID 22788954, 2012). "Our previous study suggests that the hepatocyte growth factor (HGF) released by the breast normal tissue-associated fibroblasts (NAFs) co-cultured with breast cancer cells is one of the contributing factors." (PMID 22514714, 2012). "The SPINT2, an inhibitor of HGF activator, was reported to have higher expression levels in early stage breast cancer and associated with a poor prognosis, consistent with our findings." (PMID 21060876, 2010). "Furthermore, MR analysis suggested a potential causal effect of HGF on breast cancer, particularly for the ER-negative subtype." (PMID 40665092, 2025). "Additionally, the application of MR analysis further solidifies the causal relationship between HGF and breast cancer." (PMID 40665092, 2025). "Additionally, HGF mediated the effects of Healthy Lifestyle Index (27.17%) and BMI (19.79%) on breast cancer risk." (PMID 40665092, 2025). "Multiple reports have shown that PI3K/AKT signaling is required for the expression of the COX-2 gene, and COX-2 upregulation in response to hepatocyte growth factor (HGF) signaling via this PI3K/AKT pathway has been linked to enhanced invasivity in breast cancer cells." (PMID 39511658, 2024). "Most breast cancer risk factors showed little association with HGF positivity." (PMID 34344422, 2021). "Indeed, activation of c-MET signaling in breast cancer cells promotes metastasis of breast cancer cells and secretion of HGF from tumor-associated astrocytes in the brain." (PMID 34439392, 2021). "Since highly mesenchymal TNBCs are associated with elevated expression of both FGFR1 and HGF, we assessed whether these two genes in combination could predict outcome in breast cancer patients." (PMID 33772015, 2021). "Similar mutations in the HGF promoter region also occur in breast cancer cells." (PMID 28420162, 2017). "Interestingly, a recent study by Sundaram in obese mice showed that weight loss reversed obesity-induced HGF/c-Met pathway and basal-like breast cancer progression." (PMID 28915700, 2017). "Hepatocyte growth factor has been implicated in the progression of experimental breast cancer." (PMID 29387062, 2017). "However, breast cancer cells rarely express the c-Met ligand, but often acquire HGF from stroma fibroblasts or the cancer-associated fibroblasts (CAFs) via a paracrine interaction." (PMID 29296173, 2017). "In contrast, a mutation in the HGF promoter region referred to as the deoxyadenosine tract element appears to be a frequent event, having been identified in 15% of European breast cancer patients and over 50% of African Americans with breast cancer." (PMID 25887320, 2015). "Enhanced HGF expression is specifically implicated as a promoter and risk factor in breast cancer." (PMID 26932375, 2014). "In conclusion, our study found that common variants in the SOCS4, TSLP and HGF genes might be related with breast cancer prognosis in Korean women." (PMID 25075970, 2014). "In addition, (-)-oleocanthal treatment caused a dose-dependent inhibition of HGF-induced cell migration, invasion and G1/S cell cycle progression in breast cancer cell lines." (PMID 24849787, 2014). "In this study, we found that the rs1952438 in the suppressors of cytokine signaling (SOCS4) gene, rs2289278 in the thymic stromal lymphopoietin (TSLP) gene and rs2074724 in the hepatocyte growth factor (HGF) gene were highly associated with a poor prognosis of breast cancer." (PMID 25075970, 2014). "The HGF/c-Met axis is a pathway that is linked to both obesity and breast cancer risk." (PMID 25354395, 2014).